RPS6 (ribosomal protein S6)
Diseases named in the same sentence as RPS6 in open-access papers (continued):
Sharing a sentence is not in itself a finding about the gene and the disease.
glioma (continued). "Surprisingly, 4EBP1 full protein counterparts were statistically increased in grade III gliomas and grade IV GBMs as compared to normal brain, whereas full RPS6 protein was significantly increased in the normal brain specimens as compared to grade II and grade III tumors." (PMID 25993328, 2015). "Thus, the intrinsic RPS6 can induce stem-cell-like properties in glioma cells." (PMID 35883585, 2022). "We treated IDH1 WT cell line HK157 and 2 IDH1 MT glioma cell lines, HK252 and BT142, with VPA for four days and examined phosphorylation of ribosomal protein S6 (PS6) and FASN protein expression." (PMID 39149696, 2024). "Along with a reduction in p-RPS6, combined application of MNK1/2 inhibitor and mTOR inhibitor has shown synergism against glioma growth." (PMID 33564073, 2021). "The sphere-forming ability and expression of the stem cell marker genes Nestin and Sox2 were downregulated by the knockdown of RPS6, whereas the sphere-forming ability increased in overexpression experiments in U251MG and U87MG glioma cell lines, both of which were classified as GBM, IDH-wildtype." (PMID 35883585, 2022). "Since our present results suggested that RPS6 phosphorylation might play important roles in glioma-derived extrinsic ribosome-induced GBM-RICCS formation, we next assessed RPS6 phosphorylation (ser235/236) in glioma patient tissues." (PMID 34831193, 2021).
renal cell carcinoma (9 papers, 2016 to 2023). "Interestingly, Selumetinib, a selective MEK1 inhibitor, was reported to enhance the antitumor activity of everolimusa against renal cell carcinoma by decreasing p-RPS6 and p-4E-BP1 dramatically, which caused G1 cell cycle arrest and preventing reactivation of AKT and ERK." (PMID 37035135, 2023). "Whether RSK4 could mediate the invasion and metastasis of renal cell carcinoma by rpS6 and GSK3β is also a new direction proposed by this study." (PMID 32209138, 2020). "In renal cell carcinoma (RCC), phosphorylated ribosomal protein S6, a marker of mTORC1 activation, was found to stain strongly in 85% of RCC tissues examined." (PMID 35582282, 2019).
viral infection (8 papers, 2017 to 2025). "The molecular mechanisms underlying the diverse effects of RPS6 phosphorylation on virus infection in cells needs further explanation." (PMID 31137833, 2019). "To further investigate the mechanistic action of the PI3K/mTOR signaling pathway in viral infection, we measured mTORC1 activation by monitoring the phosphorylation status of ribosomal protein S6 (pS6), a down-stream target of the mTORC1-mediated pathway." (PMID 28634408, 2017). "Different RPs like RPL10, RPL13, RPL18, RPL24, and RPS6 are involved in viral infections of plants." (PMID 33995313, 2021). "With regards to virus infection it has been shown that silencing of the RPS6 and S6K genes in N. benthamiana decreased accumulation of CMV, PVA and turnip mosaic virus (TuMV, potyvirus), which is in contrast to turnip crinkle virus and tobacco mosaic virus (TuCV and TMV respectively; tobamoviruses)." (PMID 29479362, 2018). "Additional studies are still necessary to explore the role of the nucleolar activities of RPS6 and S6K in relation to virus infections, which may also have implications for other stress responses, growth and development." (PMID 29479362, 2018). "Possibly because the experimental system that was used might have lacked sufficient sensitivity or resolution to detect changes in phosphorylation, as RPS6 in most cases of human or animal viral infections was strongly dephosphorylated within hours after infection." (PMID 30340407, 2018). "Moreover, changes in the human phosphoproteome upon viral infection highlighted several RSK target proteins in addition to c-FOS and EIF4B, such as 40S ribosomal protein S6, Tuberin/TSC2, or GSK347." (PMID 35078976, 2022). "Viral infection is only one of numerous stimuli, and RPS6 phosphorylation is a nonspecific response to virus." (PMID 31137833, 2019). "Conversely, the protease required for viral entry, TMPRSS2, was reduced upon viral infection but was not modulated by viral dose, nor were ribosomal proteins (RPL4, RPS6)." (PMID 32898168, 2020).
esophageal squamous cell carcinoma (7 papers, 2015 to 2024). Esophageal squamous cell carcinoma (ESCC) is a type of esophageal carcinoma (EC) that can affect any part of the esophagus, but is usually located in the upper or middle third. "In esophageal squamous cell carcinoma, dihydroartemisinin weakens p‐mTOR, p‐p70S6K, and p‐RPS6 to inhibit tumor growth." (PMID 38988047, 2024). "Consistent with our results, recent studies also revealed the close relationship between the high level of p-rpS6 and poor survival in esophagus squamous cell carcinoma patients, pancreatic neuroendocrine tumors and sarcoma." (PMID 26490682, 2015). "In line with our findings, downregulation of p-rpS6 are also attenuated the cells invasion in esophageal squamous cell carcinoma and renal angiomyolipoma." (PMID 26490682, 2015).
lung carcinoma (7 papers, 2015 to 2024). "For instance, the high expression of RPS6 in lung cancer is significantly related to the increased risk of early metastasis." (PMID 36004921, 2022). "The anticancer effect of RPS6-KD was reproduced in a xenograft model: A549 lung cancer cells with RPS6-KD resulted in reduced tumorigenicity with an increase in the number of SA-β-gal(+) cells in xenograft tissues." (PMID 35008473, 2021). "The suppression of proliferation by shRNA-based RPS6-KD was exaggerated by time in two lung cancer cell lines, A549 and H520." (PMID 35008473, 2021). "The anticancer effect of RPS6-KD was reproduced in a xenograft model in which A549 lung cancer cells with RPS6-KD resulted in reduced tumorigenicity with an increase in the number of SA-β-gal(+) cells in the xenograft tissues." (PMID 35008473, 2021). "The suppressive effect of short hairpin RNA (shRNA)-based RPS6-KD on cell proliferation has been observed to increase with time in two lung cancer cell lines, A549 and H520." (PMID 35008473, 2021). "Their study detected 15 Chr9 proteins highly selective for lung cancer in comparison to healthy lung tissue (i.e., RAD23B, RPS6, ARPC5)." (PMID 38539567, 2024). "Further, knockdown of RPS6 in SK-MES-1 and H1650 lung cancer cells reduced their invasive ability and decreased MMP9 and MMP2 expression, suggesting that high levels of RPS6 may promote lung cancer metastasis." (PMID 32862831, 2020).
Insulin resistance (6 papers, 2018 to 2026). Increased resistance towards insulin, that is, diminished effectiveness of insulin in reducing blood glucose levels. "Western blot analysis showed a strong reduction in ribosomal protein S6 phosphorylation in peripheral tissues (liver, muscle, and adipose) in response to injected insulin, consistent with the presence of peripheral insulin resistance." (PMID 41362820, 2026). "greater insulin resistance in KO: relatively decreased ERK, rpS6 and PRAS40 phosphorylations and ii." (PMID 32971872, 2020). "To investigate whether galangin can get insulin resistance better, we examined the phosphorylation state of ten proteins on the Akt/mTOR signal pathway, including IR, IRS1, PTEN, Akt, GSK3α, GSK3β, TSC2, mTOR, p70S6K, and RPS6." (PMID 30420897, 2018). "Moreover, basal levels of rpS6 P‐Ser240/244 were higher in bone after HFD feeding, compared to CD, suggesting that hyperactivation of mTORC1 could be involved in the development of bone‐specific insulin resistance." (PMID 33977204, 2021).
sarcoma (6 papers, 2015 to 2022). A usually aggressive malignant neoplasm of the soft tissue or bone. "The significance of p-RPS6 in these sarcoma cell lines is underlined by their sensitivity to the IGF1R inhibitor BMS-536924." (PMID 35008473, 2021). "Deforolimus decreased mTOR signaling in patients with high-grade sarcomas, as evidenced by a reduction in the amounts of the ribosomal protein S6 which is being phosphorylated in tumor sections." (PMID 36109789, 2022). "One in vitro study has shown an indirect link between RON and rpS6 in sarcoma cells, but only upon the development of resistance to an IGF1R inhibitor." (PMID 30456298, 2018). "An siRNA-based screening identified RPS6 as an effector of IGF1R inhibition in sarcoma cells." (PMID 35008473, 2021). "In this report, BMS-536924 failed to block RPS6 activation in resistant sarcoma cell lines; however, this siRNA targeting RPS6 restored BMS-53924 efficacy." (PMID 26217584, 2015).
acute myeloid leukemia (5 papers, 2010 to 2022). Acute myeloid leukemia (AML) is a group of neoplasms arising from precursor cells committed to the myeloid cell-line differentiation. "Here we show that the mTOR effectors, 4EBP1, p70S6K and rpS6, are highly activated in cultured and primary FLT3-mutated acute myeloid leukemia (AML) cells." (PMID 21067588, 2010).
colon cancer (5 papers, 2016 to 2023). "Using HEK293T cells as a positive control, we found that DRAM1 inhibited rpS6 phosphorylation in human colon cancer cells, SW480 and HCT116, with phosphorylation at Ser235/236 more significantly affected by DRAM1 than the site at Ser240/244." (PMID 30902093, 2019). "Pik3caH1047Rresults in activation of the PI3K/AKT/mTOR pathway and ERK 1/2 signaling: The epithelial cells in Fc+Pik3caH1047R and Fc+ Pik3cap110* colon cancers demonstrate increased staining for phosphorylation of RPS6 compared to those in ApcMin colon tumors." (PMID 26863299, 2016). "Analysis of TCGA colon cancer (n=461) and skin cancer (n=470) datasets revealed a positive correlation between PHF14 expression and protein translation initiation factors, eIF4E, eIF4B, and RPS6." (PMID 31040906, 2019).
lymphoma (5 papers, 2019 to 2023). A malignant (clonal) proliferation of B- lymphocytes or T- lymphocytes which involves the lymph nodes, bone marrow and/or extranodal sites. "PASK, but not RSK, was found as a potential kinase of RPS6 in these lymphomas." (PMID 35008473, 2021).
bladder cancer (4 papers, 2013 to 2023). "Several studies have found that rpS6 is phosphorylated by Akt1(Ser473) approach in colorectal and bladder cancer cells, but there are also reports revealing the Akt-independent phosphorylation of rpS6." (PMID 26490682, 2015). "In addition, kawain selectively inhibited the growth of human bladder cancer cell lines with a significant suppression of 4E-BP1 expression and rpS6 phosphorylation." (PMID 36838656, 2023).
COVID-19 (4 papers, 2022 to 2025). A disease caused by infection with severe acute respiratory syndrome coronavirus 2. "Of note, the levels of an essential downstream effector of mTOR signaling, ribosomal subunit protein S6 (Rps6), were downregulated in most of the clusters in hospitalized or severe COVID-19 samples pointing toward decreased ribosomal biogenesis." (PMID 40177636, 2025). "There was a positive correlation between COVID-19-related protein RPS6 and TAP2." (PMID 35720320, 2022).
diffuse large B-cell lymphoma (4 papers, 2012 to 2024). "Non hodgkins lymphoma: RPS6 is highly expressed in Diffuse large B cell lymphomas and genetic modulation of RPS6 protein levels with specifically targeted short hairpin RNAs (shRNA) lead to a decrease in the actively proliferating population of cells compared with control shRNA." (PMID 22709827, 2012). "High levels of RPS6 have been found in primary diffuse large B-cell lymphoma (DLBCL) cell lines and patient samples." (PMID 35008473, 2021). "Knockdown of RPS6 by shRNA was also reported to reduce the proliferation of diffuse large B-cell lymphoma (DLBCL) cell lines." (PMID 25955731, 2015).
hepatocellular carcinoma (4 papers, 2016 to 2023). A malignant tumor that arises from hepatocytes. "PD-1 binds to both RPS6 and eIF-4E to promote their phosphorylation in a hepatocellular carcinoma (HCC) cell line." (PMID 35008473, 2021). "Rather than reconstituting PIC assembly with purified components, we incubated the RNA in lysate from Huh 7.5 (human hepatoma) cells to replicate cellular conditions and then used antibodies to detect bound 43S complex components eIFs 3, 2, 1A, 1 and 40S subunit (protein rpS6)." (PMID 28009256, 2016).
acute lymphoblastic leukemia (3 papers, 2017 to 2022). Leukemia with an acute onset, characterized by the presence of lymphoblasts in the bone marrow and the peripheral blood. "This is supported by a study in pre‐B acute lymphoblastic leukaemia cells where BCI treatment inhibited RPS6 phosphorylation within 2 h." (PMID 35478300, 2022). "Our data, though limited in sample size, indicate that rRNA patterns in acute lymphoblastic leukemia cells harboring RPS6 deletion are perturbed in the same way as in cell lines with shRPS6 knockdown." (PMID 28264936, 2017).
adenoma (3 papers, 2017 to 2023). A neoplasm arising from the epithelium. "The RPS6 protein level was lower in normal ovarian tissues than in adenomas, and levels in adenomas and normal ovarian tissue were lower than those in EOC, and the differences were significant." (PMID 32862831, 2020). "All cystic and adenoma-like regions stained strongly for phosphorylation of ribosomal protein S6 (Ser240/244), indicative of Tsc1 deletion." (PMID 29133867, 2017). "In considering what features of ΔS6 livers could render them tumor-prone, we were struck by the fact that that 80% of the adenomas/tumors that we surveyed not only expressed Rps6 but also demonstrated strong immunoreactivity for phospho-Rps6Ser235/6 relative to adjacent liver." (PMID 36656901, 2023). "RPS6 was elevated in EOC compared to normal ovarian tissues and adenomas." (PMID 32862831, 2020).
Autoimmunity (3 papers, 2021 to 2025). The occurrence of an immune reaction against the organism's own cells or tissues. "The long 3′ UTR is a typical characteristic of nonsense-mediated mRNA decay (NMD) target, and RPS6 is required for autoimmunity in NMD-deficient mutant smg7." (PMID 33924988, 2021). "For example, our reannotation of the RPS6 locus is essential to understand the recurring role of RPS6 in autoimmunity." (PMID 33904405, 2021).
cervical carcinoma (3 papers, 2015 to 2021). A carcinoma arising from either the exocervical squamous epithelium or the endocervical glandular epithelium. "Downregulation of RPS6 in the cervical carcinoma cell line HeLa resulted in the inhibition of TRAIL-dependent apoptosis in a DR4-dependent manner." (PMID 35008473, 2021). "RPS6-KD in Cervical Carcinoma Cells), RPS6-KD in the human HCC cell line SK-HEP-1 suppressed TRAIL-induced apoptosis and downregulated DR4." (PMID 35008473, 2021).
head and neck squamous cell carcinoma (3 papers, 2021 to 2024). A squamous cell carcinoma that arises from any of the following anatomic sites: lip and oral cavity, nasal cavity, paranasal sinuses, pharynx, larynx, and salivary glands. "Accordingly, the accumulation of phosphorylated form of the RPS6, a typical downstream product of the mTOR pathway is one of the most frequent events in head and neck squamous cell carcinoma (HNSCC) especially in OSCC." (PMID 38370876, 2024).
mantle cell lymphoma (3 papers, 2013 to 2018). Mantle cell lymphoma is a rare form of malignant non-Hodgkin lymphoma affecting B lymphocytes in the lymph nodes in a region called the ``mantle zone''. "In mantle cell lymphoma (MCL), AICAR-mediated stimulation of AMPK activity dampened phosphorylation of critical downstream effectors of mTOR signaling, such as 4E-BP1 and ribosomal protein S6, leading to cell growth inhibition." (PMID 30274374, 2018).
non-Hodgkin lymphoma (3 papers, 2012 to 2022). Distinct from Hodgkin lymphoma both morphologically and biologically, non-Hodgkin lymphoma (NHL) is characterized by the absence of Reed-Sternberg cells, can occur at any age, and usually presents as a localized or generalized lymphadenopathy associated with fever and weight loss. "Indeed, highly expressed rpS6 was observed in non-Hodgkin lymphoma, and rpS6 activation was responsible for drug resistance in human cancers." (PMID 30902093, 2019).
psoriasis (3 papers, 2015 to 2021). An autoimmune condition characterized by red, well-delineated plaques with silvery scales that are usually on the extensor surfaces and scalp. "The activation of mTORC1 and its downstream signalling molecules S6K1 and ribosomal protein S6 was discovered in the skin lesions of patients with psoriasis." (PMID 34456715, 2021). "Ribosomal protein S6, which is both a key mediator of mTOR function and coordinate regulator of ribosome function and biogenesis, is hyperactivated and abnormally phosphorylated in epidermal lesions of patients with psoriasis." (PMID 34344401, 2021). "Consistent with this, S6K1 (Thr389) is activated in psoriasis lesions and ribosomal protein S6 is activated at multiple phosphorylation sites, with S6 (Ser235/236) more active in the suprabasal epidermis and S6 (Ser240) active throughout the epidermis and basal layer." (PMID 26251673, 2015).
Rett syndrome (3 papers, 2011 to 2015). A severe neurodevelopmental disorder affecting the central nervous system. "Ribosomal protein S6 (RPS6) is phosphorylated in response to an array of growth factors and mitogens, a process that may be disrupted in Rett Syndrome." (PMID 21915259, 2011). "Finally, altered rpS6 phosphorylation has been reported in rodents following spontaneous seizures and traumatic brain injury and in humans in several neurodevelopmental disorders including Down syndrome, Tuberous sclerosis, Autism, and Rett syndrome." (PMID 26733799, 2015).
sarcopenia (3 papers, 2016 to 2024). Progressive decline in muscle mass due to aging which results in decreased functional capacity of muscles. "Inadequate nutritional intake can downregulate the Akt/mTORC1 signaling pathway, thus reducing muscle protein synthesis by inhibiting the phosphorylation of the downstream markers p70S6K and rpS6, and ultimately resulting in sarcopenia." (PMID 39286235, 2024). "In the present study after RWE (that prevented sarcopenia in the quadriceps), we did not observe increased levels of pAKT, pS6K1, or p-rpS6 for either sex." (PMID 27964759, 2016). "However, when we examined mTORC1 signaling in skeletal muscles in rats at ages where sarcopenia occurs, we were surprised to see that the level of signaling had increased rather than decreased—there was an age-related increase in the phosphorylation of S6K1 and rpS6, readouts of mTORC1 activity." (PMID 31308131, 2019).